HMGA1 (high mobility group AT-hook 1)
Diseases named in the same sentence as HMGA1 in open-access papers (continued):
Sharing a sentence is not in itself a finding about the gene and the disease.
colorectal cancer (39 papers, 2014 to 2025). A primary or metastatic malignant neoplasm that affects the colon or rectum. "HMGA1 expression has been reported to be increased in colorectal cancer and can serve as a diagnostic indicator for CRC." (PMID 39028420, 2024). "Altogether, these findings suggest that SAC gene overexpression induced by HMGA1 may have a role in colorectal cancer progression causing chromosome instability." (PMID 26009897, 2015). "Other research of HMGA1 shows that HMGA1 has been identified as a target of miR-296-5p, which involves in cell proliferation in colorectal cancer." (PMID 38706894, 2024). "In colorectal cancer, PD-L1 upregulates HMGA1 to activate PI3K/Akt and MEK/ERK pathways to promote cancer stem cell expansion." (PMID 36922519, 2023). "HMGA1 as an oncogene, is often expressed in digestive tract tumours, such as liver cancer, colorectal cancer, pancreatic cancer and gastric cancer 82-85." (PMID 35864955, 2022). "In colorectal cancer cells, H19 mediates miR-138 by sponging it and subsequently enhances the expression of HMGA1, thereby enhancing the invasion ability of cancer cells." (PMID 34583640, 2021). "LINC00460 directly interacts with IGF2BP2 and DHX9 to assist the recognition protein IGF2BP2 to recognize and stabilize HMGA1 mRNA, enhance the protein expression of HMGA1, and promote the proliferation and metastasis of colorectal cancer." (PMID 33926508, 2021). "HMGA1 interacted with β-catenin to positively regulate Wnt/β-catenin signaling in colorectal cancer cells." (PMID 27534621, 2016). "It has been observed that RAS oncogene, activated in a large set of colorectal carcinomas, plays an important role in the modulation of HMGA1 expression." (PMID 25859543, 2015). "The role of HMGA proteins in cancer and, in particular HMGA1, has been widely evaluated in colorectal carcinomas." (PMID 25859543, 2015). "It is worth noting that HMGA1 expression (percentage of cells and intensity) increased gradually from pre-malignant stages of colorectal carcinoma to adenoma (characterized by mild to severe atypia) up to carcinoma." (PMID 25859543, 2015). "The lncRNA 00460/IGF2BP2 complex May promote colorectal cancer cell proliferation by mediating high mobility group AT-hook 1 (HMGA1) transcript stability through METTL3-dependent m6A modification." (PMID 40986143, 2025). "In addition, HMGA1-mediated transcriptional activation of GLUT3 is responsible for oncogenic functions of caveolin 1 in colorectal cancer." (PMID 40787462, 2025). "In many cancer types, including colorectal cancer, HMGA1 is overexpressed." (PMID 39895631, 2025). "Additionally, HMGA1 upregulation promoted colorectal cancer cell growth by boosting Wnt/β-catenin signaling." (PMID 36635290, 2023). "In a colorectal cancer study, researchers showed that HMGA1 could be targeted by miR-26a to modulate the expression." (PMID 35114891, 2022). "Similarly, in colorectal cancer, HMGA1 promotes EMT and metastases by positively regulating Wnt/β-catenin signaling." (PMID 35054987, 2022). "Moreover, LINC00460 was found to interact with IGF2BP2 in promoting the proliferation and metastasis of colorectal cancer by increasing the stability of HMGA1 mRNA via an m6A-mediated modification." (PMID 36438499, 2022). "Previous studies have shown that H19 promotes cancer development through different mechanisms, as examples: in gastric cancer through Fas-related protein, in cholangiocarcinoma through IL-6 and CXCR4, in colorectal cancer through HMGA1, and in multiple myeloma through P50/P65." (PMID 34843522, 2021). "Furthermore, miR-214 mediates the downregulation of HMGA1 to inhibit growth and motility in human cervical and colorectal cancer cells." (PMID 29093516, 2017).
colorectal cancer (continued). "This complex may increase the stability of HMGA1 mRNA by recognizing the m6A modification site of HMGA1 (high-mobility group at-hook 1), thereby enhancing the expression of HMGA1, and ultimately promoting the proliferation, migration, and invasion process of colorectal cancer cells." (PMID 35070987, 2021). "In colorectal carcinoma (CRC), IGF2BP2 binds the 3' untranslated region (3' UTR) of HMGA1, augmenting its stability and driving tumor growth and metastasis." (PMID 41041073, 2025). "LINC00460/DHX9/IGF2BP2 complex stimulates colorectal cancer proliferation and metastasis by interacting with IGF2BP2 and regulating HMGA1 mRNA stability by m6A modification." (PMID 37744330, 2023). "For example, HMGA1, whose expression was significantly correlated with ESC differentiation and the referential stem values of colorectal cancer in our study, is also reported to be highly expressed in human ESCs and poorly differentiated, stem-like cancers." (PMID 35313979, 2022). "In colorectal cancer cells, caveolin 1 (CAV1) overexpression boosts aerobic glycolysis through HMGA1-induced GLUT3 transcription." (PMID 35054987, 2022). "PD-L1 is also very expressed in colorectal cancer cells and interacts with HMGA1 to activate HMGA1-dependent pathways, mainly including the PI3K/Akt and MEK/ERK pathways, and it ultimately maintain the self-renewal of colorectal cancer cells." (PMID 35864955, 2022). "In human intestine, HMGA1 and SOX9 are positively correlated, and both become upregulated in colorectal cancer." (PMID 28452345, 2017). "HMGA1 and ASCL2 are upregulated and coexpressed in human colorectal cancer." (PMID 39895630, 2025). "Further, HMGA1 and ASCL2 are coexpressed and upregulated in human colorectal cancer." (PMID 39895630, 2025). "Moreover, both HMGA1 and SOX9 are positively correlated in human intestinal epithelium, and both become markedly upregulated in colorectal cancer." (PMID 28452345, 2017). "Because HMGA1 is overexpressed in diverse epithelial cancers and correlates with cancer stem cell properties in experimental models, we also sought to determine whether HMGA1 and SOX9 are co-regulated in colorectal cancer." (PMID 28452345, 2017). "Indeed, in tumor cells from colorectal cancer, GLUT3 was induced by caveolin‐1, in a HMGA1‐dependent manner, HMGA1 enhancing GLUT3 transcription by binding to specific sites within its promoter region." (PMID 28923827, 2017). "Thus, there are multiple distinct mechanisms that could give rise to overexpression of HMGA1 and SOX9 in colorectal cancer, and SOX9 may depend, at least in part, on genetic lesions distinct from HMGA1 overexpression in this setting." (PMID 28452345, 2017). "Strikingly, both HMGA1 and SOX9 are markedly upregulated in human colorectal cancer (P<0.0000001), although their expression was not correlated in this setting." (PMID 28452345, 2017). "The observation of HMGA1 upregulation in colon cancer dates back to 1996, when our group detected the HMGA1 proteins, previously called HMGI(Y), in human colorectal cancer cell lines and tissues but not in normal intestinal mucosa." (PMID 24833610, 2014). "Although HMGA1 and SOX9 are positively correlated in normal colonic epithelium and both become upregulated in cancer, it is not surprising that the correlation is lost in colorectal cancer." (PMID 28452345, 2017).
gastric cancer (39 papers, 2011 to 2025). A primary or metastatic malignant neoplasm involving the stomach. "HOTTIP, an exosomelncRNA, promotes its target HMGA1 in gastric cancer (GC) cells, causingEMT and cisplatin resistance." (PMID 38108852, 2024). "After identifying tumorigenic proteins associated with HMGA1, we assessed the prognostic value of HMGA1 in gastric cancer." (PMID 35629376, 2022). "Based on our findings, HMGA1 was significantly and positively associated with N-cadherin and fibronectin in gastric cancer, contributing to tumor invasiveness and ultimately indicating a poor prognosis." (PMID 35629376, 2022). "A recent study demonstrates that HMGA1 stimulates gastric cancer proliferation and metastasis via transactivating SUZ12 and CCDC43 expression." (PMID 38706894, 2024). "Our results suggested that YWHAH can promote the proliferation of gastric cancer cells by activating the HMGA1/PI3K/AKT/mTOR signaling pathway through Fra-1." (PMID 37415737, 2023). "AC constrained gastric cancer cell proliferation and migration and promoted endoplasmic reticulum stress by regulating HMGA1." (PMID 35692504, 2022). "Taken together, AC restrained gastric cancer cell aggressive behaviors and promoted endoplasmic reticulum stress by regulating HMGA1." (PMID 35692504, 2022). "lncRNA GACAT3, as a competitive endogenous RNA of HMGA1, can alleviate cucurbitacin B-induced apoptosis in gastric cancer cells." (PMID 35082972, 2022). "Asiaticoside suppressed gastric cancer cell aggressive behaviors and stimulated endoplasmic reticulum stress via regulating the expressions of miR-635 and HMGA1." (PMID 35692504, 2022). "In gastric cancer (GC) cells, the exosomal lncRNA HOTTIP activates its target HMGA1, causing GC cells to undergo EMT and acquire cisplatin resistance." (PMID 35359397, 2022). "AC suppressed gastric cancer progression and induced endoplasmic reticulum stress via the miR-635/HMGA1 axis, providing a valuable drug against gastric cancer." (PMID 35692504, 2022). "In the present study, we evaluated the prognostic value of HMGA1 in gastric cancer and its relationship with cancer invasiveness." (PMID 35629376, 2022). "In gastric cancer, HMGA1 and the c-Myc promoter contribute to induce c-Myc expression, thereby promoting aerobic glycolysis." (PMID 35864955, 2022). "In gastric cancer, HMGA1 overexpression enhances the migration and invasion abilities and promotes epithelial-to-mesenchymal transition of cancer cells." (PMID 36685838, 2022). "Previous studies showed that HMGA1 functioned as an oncogene and promoted gastric cancer progression." (PMID 35692504, 2022). "We thereby show for the first time that HMGA1 expression has a substantial value as a biomarker of response to chemotherapy in gastric cancer." (PMID 35049679, 2021). "al demonstrated that SNHG22 induces migration, invasion and angiogenesis of gastric cancer cells via miR-361-3p/HMGA1/Wnt axis." (PMID 34663788, 2021). "Huang et al39 demonstrated that TRPM2‐AS took important regulatory parts in gastric carcinoma development by functioning as a ceRNA to regulate HMGA1 via sponging miR‐195." (PMID 32583631, 2020). "HMGA1 (High mobility group AT-hook 1) is an oncogene that is induced by Wnt/beta-catenin pathway and which positively regulates cell proliferation in gastric cancer." (PMID 24564251, 2013). "Similarly, MiR-195 down-regulation promotes 5-fluorouracil (5-FU) resistance in gastric cancer by upregulating HMGA1 expression, thereby contributing to acquired drug resistance." (PMID 40251829, 2025). "This aligns with multiple studies showing elevated HMGA1 levels in various cancers, including esophageal, colorectal, breast, and gastric cancers, where high HMGA1 expression correlates with advanced disease and poorer prognosis, underscoring its role in tumor progression and metastasis." (PMID 41145488, 2025).
gastric cancer (continued). "Similarly, HMGA1 promoting gastric cancer oncogenic and glycolytic phenotypes by regulating c-myc expression and identify a novel function of HMGA1 in regulating aerobic glycolysis in gastric cancer." (PMID 38706894, 2024). "Notably, IGF2BP2 has been found to target SIRT1, ZEB1, and HMGA1, thereby promoting gastric cancer growth and metastasis." (PMID 37865637, 2023). "High HMGA1 expression indicates a poor prognosis for gastric cancer." (PMID 35629376, 2022). "Moreover, patients affected by gastric cancer and with high levels of HMGA1 expression in the tumor, had remarkably better OS when undergoing treatment with platinum- and/or fluoropirimidine-based chemotherapy." (PMID 36614035, 2022). "The aim of this work was to evaluate the clinical value of HMGA1 in gastric cancer." (PMID 35049679, 2021). "It was reported that TRPM2-AS located in the cytoplasm could sponge miR-195 to promote the expression of HMGA1 (target gene of miR-195), thereby playing a tumor promoter role in gastric cancer." (PMID 34696681, 2021). "ELK1 induced TRPM2-AS and enhances the growth of gastric cancer cells via miR-195/HMGA1 signaling." (PMID 34455918, 2021). "HMGA1 expression was analyzed by IHC in 323 gastric carcinomas." (PMID 35049679, 2021). "High HMGA1 expression was observed in 223 (69%) gastric carcinoma cases." (PMID 35049679, 2021). "In gastric cancer, there is relatively little research on HMGA1." (PMID 30614613, 2019). "However, analysis of a larger number of human specimens may provide further evidence for the role of HMGA1 in gastric cancer." (PMID 35629376, 2022). "Therefore, we inferred that HMGA1 might exert function in the modulation of AC on gastric cancer progression." (PMID 35692504, 2022). "We used the TCGA data to verify our hypothesis that the expression of miRNA Let‐7a in gastric cancer tissue was downregulated, and the expression of HMGA1 and LINC00152 was upregulated, which showed that our previous hypothesis, i.e., HMGA1‐Let‐7a‐LINC00152 is a ceRNA, was correct." (PMID 35014092, 2022). "Similarly, HMGA1 was also reported to maintain cell proliferation in gastric cancer." (PMID 25983750, 2015). "We performed cDNA microarray analysis to identify the downstream target genes of SOX2 in gastric cancer cells, and found that many tumor-associated genes exhibited significant changes in expression after SOX2-overexpression (e.g., LTF, PPP2R1B, TGFBR2, SERPINE1, MMP9, HMGA1 and SOX9)." (PMID 21304604, 2011). "For instance, miR-361-3p represses gastric cancer cell proliferation, invasion, and migration, and HUVEC angiogenesis via down-regulating HMGA1 to disrupt the Wnt/β-catenin pathway." (PMID 38055382, 2023). "However, the relationship between HMGA1 expression and gastric cancer development remains unclear." (PMID 35629376, 2022). "A previous in vitro study reported that HMGA1 regulates EMT and accelerates the development of gastric cancer." (PMID 35629376, 2022). "Previous studies have reported a relationship between HMGA1/HMGA2 and gastric cancer." (PMID 35629376, 2022). "However, the role of HMGA1 in the growth and metastasis of gastric cancer (GC) has not yet been elucidated." (PMID 34167089, 2021). "However, HMGA1 is not specifically expressed in gastric cancer." (PMID 35629376, 2022).
lung cancer (31 papers, 2012 to 2025). A malignant neoplasm involving the lung. "HMGA1 up-regulation is frequently observed in many cancer types, including lung cancer, and linked to poor survival." (PMID 39134516, 2024). "Overexpression of the HMGA1 gene, as well as increased levels of the protein encoded by this gene, was confirmed in many different lung cancer cell lines compared to normal epithelium bronchitis." (PMID 35948739, 2022). "As mutations or copy number changes of the HMGA1 appear to occur rarely in lung cancer, potential causes of HMGA1 overexpression were sought." (PMID 35805937, 2022). "Induction of IL-24, a novel tumor suppressor cytokine in the H1299 lung cancer cell line, was associated with markedly reduced HMGA1 expression level, miR22-3p and -5p levels with a concomitant decrease in pAKT expression." (PMID 35948739, 2022). "Overexpression of HMGA1 has been shown to be associated with tumor progression and metastasis in several cancers, including human lung cancer." (PMID 27602961, 2016). "Studies have shown that overexpression of HMGA1 proteins is associated with lung cancer metastasis through transcriptional upregulation of genes involved in the promotion of metastasis in various tumor types." (PMID 27602961, 2016). "We selected seven genes [4 unique genes (E2F6, TFDP1, SUV39H1, and HNRPD) for NSCLC and 3 genes (RBL1, IRF1, and HMGA1) for general events] for validation as diagnostic markers in lung cancer." (PMID 24564251, 2013). "However, not all studies conducted so far have confirmed the association between the amount of HMGA1 protein in neoplastic tissue and the survival time of lung cancer patients." (PMID 35948739, 2022). "Since cigarette smoke affects DNA methylation and thus is a critical factor in the development of lung cancer, it may, at least partially, account for the observed differences in HMGA1 expression levels associated with smoking habits." (PMID 35805937, 2022). "It revealed that HMGA1 gene alterations were stated in only 1.1% of lung cancer patients profiled for copy number changes, mutations, and structural variants of the gene, namely in about 1.5% of lung adenocarcinoma and 0.5% of lung squamous cell carcinoma cases." (PMID 35805937, 2022). "HMGA1 overexpression has been identified in a number of cancer types, and this abnormality has been associated with a poor prognosis in patients with gliomas, pancreatic cancer and lung cancer." (PMID 34831413, 2021). "Growing evidence has illustrated the association between HMGA1 overexpression and cancer metastasis in a range of human cancers, such as colorectal cancer, ovarian cancer, head and neck tumor, glioblastomas, pancreatic cancer, breast cancer, prostate cancer, and lung cancer." (PMID 27602961, 2016). "A similar ‘buffer’ effect of HMGA1 on inflammatory signalling is also detected in lung cancer cells." (PMID 39134516, 2024). "With HMGA1 overexpression being a common feature of lung cancer, the study then examined the molecular mechanisms responsible for its upregulation." (PMID 35805937, 2022). "Our present reanalysis using currently available data by Oncomine and TNMplot found that HMGA1 is overexpressed in lung cancer in comparison to unpaired normal lung tissue and to the non-cancerous tissue adjacent to the tumor." (PMID 35805937, 2022). "Expression of both the HMGA1 gene and the HMGA1 protein has been found to be upregulated in various lung cancer cell lines in comparison with normal human lung bronchial epithelium." (PMID 35805937, 2022). "The expression of both the HMGA1 gene and the HMGA1 protein was proved to be up-regulated in many different lung cancer cell lines compared with normal human lung bronchial epithelium cells." (PMID 35948739, 2022).